DDR1 (discoidin domain receptor tyrosine kinase 1)
Diseases named in the same sentence as DDR1 in open-access papers (continued):
Sharing a sentence is not in itself a finding about the gene and the disease.
tumor (continued). "Moreover, we identified that collagen-induced DDR1 activation enhanced aggressive tumor phenotypes, and that a pharmacologic inhibition of DDR1 can suppress cancer progression in vitro and in vivo." (PMID 28143619, 2017). "Discoidin domain receptor 1 (DDR1), a receptor tyrosine kinase that utilizes collagen as a ligand, is a key molecule in the progression of solid tumors as it regulates the interaction of cancer cells with the tumor stroma." (PMID 28143619, 2017). "Therefore, in vivo experiments were widely performed to examine the roles of DDR1 and its related signaling in tumor development." (PMID 28743276, 2017). "The overexpression of DDR1 in these different human cancers support the hypothesis that DDR1 may impact tumorigenesis and/or tumor progression." (PMID 26297342, 2015). "DDR1 knockdown impaired tumor cell proliferation and migration in vitro and tumor growth in vivo." (PMID 25369402, 2014). "DDR1 silencing also impaired subcutaneous xenograft tumor growth in mice." (PMID 25369402, 2014). "Here, we report that silencing of DDR1 inhibited BXPC3 tumor cell growth and migration in vitro." (PMID 25369402, 2014). "The three DDR1 mutations we identified in EC consisted of two missense mutations (DDR1R570Q and DDR1R574S), and a frameshift mutation (DDR1N740Ifs*10) that occurred in an MSI-positive tumor." (PMID 25427824, 2014). "We demonstrated that silencing of DDR1 results in an upregulation of TGFBI that could block tumor cell growth and motility, while exogenous addition of TGFBI into tumor cells recapitulated those phenotypes." (PMID 25369402, 2014). "We also investigated some genes frequently associated with collective (DDR1, eIF4GI) and mesenchymal migration (Snai3), but found no significant expression difference between our tumor types." (PMID 22748014, 2012). "Moreover, DDR1 protein expression was correlated with the pathologic grade of the tumor and the clinical disease stage at the time of surgery." (PMID 21541037, 2011). "The overexpression of DDR1 in these different human cancers suggests that it may have a function in tumor progression." (PMID 21541037, 2011). "However, our studies also indicate that DDR1 is rather involved in the process of tumor invasion than in tumor growth." (PMID 20799954, 2010). "One reason might be that HCC is a very heterogeneous tumor entity and distinct cellular components might interfere with the effect of miR-199a-5p on DDR1." (PMID 20799954, 2010). "However, our study demonstrates a previously uncharacterized biological function of miR-199a-5p such as the ability to inhibit tumor invasion through targeting DDR1." (PMID 20799954, 2010). "Indeed, DDR1 inhibitors have been widely used in preclinical tumor models." (PMID 40248197, 2025). "Firstly, DDR1 could act as both a tumor suppressor or promoter depending on cellular contexts." (PMID 40456688, 2025). "Given that targeting DDR1 kinase activity alone cannot fully block the biological effects mediated by its scaffold function, inducing DDR1 degradation may overcome the limitations of DDR1 inhibitor accessibility, thereby effectively inhibiting the growth of DDR1-high expressing tumor cells." (PMID 40713963, 2025). "These consistent negative associations imply that DDR1 may interfere with cell-intrinsic death pathways and impair DNA repair capacity, which could facilitate genomic instability while allowing tumor cells to evade cytotoxic stress." (PMID 40869052, 2025). "Furthermore, cell-type–specific analyses showed DDR1 enrichment within myeloid-derived suppressor cells (MDSC) and M2-polarized tumor-associated macrophages, aligning with its proposed role in fostering an immunosuppressive and exclusionary tumor microenvironment." (PMID 40869052, 2025).
tumor (continued). "For instance, the triple‐helical structure of collagen binds to cell surface receptor tyrosine kinases, specifically Discoidin domain receptor (DDR1/2), which in turn promotes cancer cell survival and tumor progression, indicating that it might be a therapeutic target." (PMID 40437741, 2025). "In addition, DDR1 reportedly regulates tumor cell chemoresistance." (PMID 38177123, 2024). "Thus, the combination of serum DDR1 and tumour DDR1 levels with other monitoring methods, such as alpha fetoprotein (AFP), computed tomography (CT) or magnetic resonance imaging (MRI), might be helpful in forecasting recurrence." (PMID 37007062, 2023). "Indeed, high level of DDR1 expression has been observed in several tumors such as prostate, lungs, breast, and ovary, suggesting a potential role of DDR1 in tumorigenesis and tumor progression." (PMID 35205677, 2022). "Finally, they could validate DDR1 as a therapeutic target for tumor immunotherapy by generating a blocking anti-DDR1 antibody." (PMID 35936735, 2022). "However, DDR1 specifically interacts with collagen in cell proliferation, differentiation, migration, and inflammatory response during chronic diseases such as pulmonary, kidney and vascular infection, and is more specifically overexpressed in tumor state." (PMID 35267698, 2022). "In our study, DDR1 expression was detected in 66 of 94 (70.2%) patients with PCa and was significantly correlated with high Gleason score (P < 0.001), advanced pathological tumour stage (P = 0.024), distal metastases (P < 0.001) and shorter overall survival (P = 0.028)." (PMID 33239676, 2021). "However, the impact of DDRs in tumor development or metastasis seems to be cancer-dependent and may be explained by the DDR1 isoform expressed or by interaction with other receptors." (PMID 33917302, 2021). "Meanwhile, miR-199b-5p restoration or DDR1 silencing can induce a transition from a mesenchymal-like toward a more cobblestone-like epithelial phenotype, as supported by the E-cadherin overexpression and the downregulation of vimentin and fibronectin expression in PCa cells and xenograft tumours." (PMID 33239676, 2021). "Furthermore, DDR1 increases cell–cell adhesion; hence, we can hypothesize a role of DDR1 in the adhesion of tumor cells to protective cells such as platelets, CAFs, or immune cells." (PMID 33917302, 2021). "DDR1 silenced livers developed less metastatic foci than DDR1-expressing ones, which may suggest that depletion of DDR1 in the sinusoids creates a less favorable microenvironment for tumor implantation and colonization." (PMID 33110221, 2020). "Furthermore, we find that both freshly isolated, quiescent and tumor-activated HSCs express DDR1." (PMID 33110221, 2020). "However, selective DDR1 inhibitors displayed limited anti‐tumor effect." (PMID 31116512, 2019). "Thus, considering the inverse nature of the relationship between miR-486-3p and DDR1, it seems highlylikely that miR-486-3p may act as a tumor suppressor through inhibiting DDR1 expression in OSCC." (PMID 31253192, 2019). "Therefore, short-term use of DDR1 inhibitors or strategies to target DDR1 in tumour cells might be required to limit toxicity." (PMID 31717573, 2019). "Finally, DDR1 activity may play a role in metastasis growth, as suggested by the anti‐tumour effect and reduction in ctDNA levels and luciferase signals in animals with detectable metastases treated with nilotinib." (PMID 29438985, 2018). "Moreover, DDR1 was reported to decrease the sensitivity to chemotherapy and induce survival signals, which may lead to neoplasm recurrence." (PMID 28743276, 2017). "However, due to collogen-dependent activation of DDR1, the behaviors of DDR1 may also rely on tumor microenvironment." (PMID 28743276, 2017).
tumor (continued). "Notably, both IGF-IR and DDR1 have been implicated in the induction and maintenance of epithelial-mesenchymal transition (EMT), one hallmark of stem cells and a critical process allowing tissue remodeling during embryogenic and tumor invasion and metastasis." (PMID 26655502, 2016). "Silencing DDR1 disrupted this complex, alleviating MUFA-mediated ferroptosis inhibition and subsequently increasing tumor immunogenicity." (PMID 40993737, 2025). "Preclinical blockade of DDR1 restructures collagen, enhances CD8+ T cell penetration, and suppresses tumor growth; monoclonal antibodies against the DDR1-ECD can even induce complete tumor regression while boosting interferon-γ (IFN-γ) production." (PMID 40869052, 2025). "Collectively, these findings suggested that combined DDR1 inhibition and CIR induced ferroptosis-driven tumor cell death in HNSCC." (PMID 40993737, 2025). "KI-301690 inhibits the expression of ECM components, including collagen, fibronectin, and vimentin, by blocking the DDR1/PYK2/FAK signaling pathway, significantly reducing tumor growth in a pancreatic xenograft model when combined with gemcitabine." (PMID 40563472, 2025). "DDR1 and DDR2 are pivotal in bridging cancer cells with ECM, driving tumor progression through diverse mechanisms." (PMID 40563472, 2025). "Other studies have shown that DDR1 can promote matrix metalloproteinases (MMPs) secretion to induce extracellular matrix (ECM) degradation and tumor metastasis, while its inhibition has been reported to hamper metastatic colonization." (PMID 40458187, 2025). "Downstream, CXCL5-triggered PI3K/AKT signaling and DDR1-dependent JNK activation converge to elevate PD-L1 expression, thereby reinforcing an immunosuppressive tumor microenvironment (TME)." (PMID 40869052, 2025). "Consistent with the seed and soil theory of metastasis, DDR1 expression on cancer cells enhances their ability to localize to tissues rich in collagen III, such as the airway smooth muscle, aiding in tumor colonization." (PMID 40563472, 2025). "In a triple-negative breast cancer mouse model, DDR1 knockout enhanced CD8+ and CD4+ T-cell infiltration, increased IFN-γ production, disrupted peripheral collagen organization, and suppressed tumor growth." (PMID 41394854, 2025). "Furthermore, combination therapy may further improve the anti-tumor activity of DDR1 inhibitors." (PMID 40456688, 2025). "DDR1 inhibitors can overcome ECM-mediated drug resistance by disrupting DDR1/PYK2/FAK signaling, remodeling the tumor microenvironment, and enhancing the efficacy of conventional chemotherapeutic agents." (PMID 41394854, 2025). "In vitro validation and pathological analysis revealed that DDR1 has a significant effect on the biological function of NSCLC cancer cells, promoting tumor cell proliferation, migration and invasion." (PMID 41394854, 2025). "Tumor-derived type III collagen maintains tumor dormancy; its disruption reactivates tumor cell proliferation via DDR1-mediated STAT1 signaling and facilitates metastasis." (PMID 41375062, 2025). "miR-199b exhibits tumor-suppressive activity in TNBC by inhibiting proliferation and invasion through the downregulation of DDR1." (PMID 41009685, 2025). "Therapeutically, antibodies targeting DDR1 disrupt collagen organization, facilitating T cell entry and increasing IFN-γ production, leading to potent tumor regression in preclinical models." (PMID 40869052, 2025). "To compare gene expression between the high and low DDR1 expression groups, we identified 382 upregulated and 1,749 downregulated DEGs in NSCLC tumor samples from the TCGA database." (PMID 41394854, 2025). "MyCAF-secreted COL-I promotes proliferation and tumor development through increased stiffness and TAZ activation in pretumoral hepatocytes and through the activation of DDR1 in established tumors." (PMID 40248197, 2025).
tumor (continued). "Enrichment analysis of the DDR1-high and DDR1-low groups revealed enrichment of the cell cycle and PI3K–Akt signaling pathways, both of which are well-established drivers of tumor proliferation, survival, and therapeutic resistance in NSCLC." (PMID 41394854, 2025). "Upon activation, DDR1 and DDR2 regulate cell proliferation, differentiation, and ECM responses, contributing to tumor progression through altered gene expression." (PMID 40721833, 2025). "DDR1-ECD-neutralising antibodies disrupt collagen fibre alignment, enhance immune cell infiltration and suppress tumor growth." (PMID 40519272, 2025). "Mechanistically, DDR1 activation reorganizes the ECM, a prerequisite for tumor expansion and dissemination." (PMID 40869052, 2025). "The cleaved form of collagen I was found to promote PDAC progression by activating the DDR1–NFκβ–NRF2 pathway, whereas intact Collagen I inhibits tumor growth by triggering DDR1 degradation." (PMID 40437741, 2025). "Our study demonstrated that DDR1 promotes tumor progression and immune evasion and is frequently overexpressed in NSCLC patients, suggesting that DDR1 is a potential prognostic biomarker and therapeutic target." (PMID 41394854, 2025). "In this study, we innovatively validated the specific mechanism of DDR1 in mediating MMDR in CRC and proposed an effective strategy to enhance the antitumor efficacy by actively modulating the tumor collagen matrix during chemotherapy." (PMID 38953306, 2024). "In PDAC, the DDR1–NF-κB–p62–NRF2 cascade can be activated by cleaved collagen I which limits metabolism and growth of tumours." (PMID 38659022, 2024). "Their study revealed that ablating DDR1 in TNBC mouse models enhanced intratumoral T cell infiltration and suppressed tumor growth." (PMID 39513932, 2024). "Because RhoA/ROCK1 signaling is also closely related to tumor EMT and metastasis, we further investigated the role of HIF‐1α in DDR1‐induced EMT and metastasis in GC." (PMID 39024501, 2024). "DDR1 and DDR2, which belong to the receptor tyrosine kinase (RTK) family, are expressed by both tumor cells and some immune cells." (PMID 38946426, 2024). "Recently, the humanized DDR1 antibody PRTH-101 has been proven to destroy collagen fiber alignment and increase CD8+ T-cell infiltration in tumor-bearing mice." (PMID 38946426, 2024). "For example, DDR1 is highly expressed in GBM and leads to the resistance of tumor cells to radiotherapy and chemotherapy by affecting the Akt and mTOR signaling pathways." (PMID 37031216, 2023). "Accordingly, lower levels of DDR1, MFN2 and OPA1 and higher levels of pAMPK were detected in WM983B and A375M2 tumours, compared to WM983A and A375P tumours as shown in vitro." (PMID 37217519, 2023). "As reported, the DDR1 extracellular domain contributes significantly to immune exclusion, providing great obstacles for immune cells’ infiltration into cancer tissue; thus, targeting DDR1 via monoclonal antibody could reverse this situation and provide a strategy for tumor treatment." (PMID 36992198, 2023). "As expected, DDR1 overexpression compromised EFL1-induced pharmacological effects on liver dysfunction, ascites, body weight, tumor weight, tumor volume and tumor morphology." (PMID 37709489, 2023). "In contrast, researchers have found that it is the extracellular DDR1 collagen-binding domain (ECD), the one required for tumor growth in immunocompetent hosts." (PMID 37284199, 2023). "Significant correlations were observed between the expression of DDR1, EGFR, and SRC/BCR axis, indicating its active involvement in COAD [source: GEPIA; datasets, TCGA (tumor), GTEx (Normal)]." (PMID 35664781, 2022). "To examine the clinical relevance of DDR1 and ARF6 in HCC, we evaluated the protein and phosphorylation levels of DDR1 and ARF6-GTP in a cohort of 50 paired HCC tissues and peripheral non-tumor tissue samples from Tongji hospital by western blot." (PMID 35140331, 2022).
tumor (continued). "In vivo, mice treatment with imatinib, a tyrosine kinase inhibitor (TKi) known to target DDR1/2 activity, improved anti-BRAFV600E drug efficacy and delayed tumor relapse." (PMID 35936735, 2022). "Careful spatial assessment of tumors revealed that DDR1 prevents penetration of CD8 T cells into the tissue core, trapping T cells at the margins of the tumor mass." (PMID 35027528, 2022). "The expression of RTKs, including DDR1, PDGFRβ, and VEGFR2, resulted in overcoming MEK-ERK inhibition allowing reactivation of tumor cell growth." (PMID 34958800, 2022). "Tumor-derived type III collagen is necessary to sustain tumor dormancy, as its interference restores tumor cell proliferation through DDR1-mediated STAT1 signaling." (PMID 36430404, 2022). "In pancreatic cancer, collagen stimulated CXC chemokine ligand-5 (CXCL5) production through the DDR1/PKCθ/spleen tyrosine kinase (SYK)/nuclear factor κB (NF-κB) pathway, which induced neutrophil extracellular traps (NETs) to drive tumor metastasis." (PMID 35935941, 2022). "Comparing the relative expression of selective genes between COAD, LGG, and GBM, we observed DDR1 and beta-catenin (CTNNB1) genes to be elevated in all three tumor types." (PMID 35664781, 2022). "In many cancers, DDR1 or DDR2 are overexpressed, suggesting a role for DDRs in tumor development and metastasis." (PMID 33917302, 2021). "Conversely, in MDA-MD-231 cells, MT1-MMP has a protective effect through degradation of collagen I and cleavage of DDR1, altering the collagen/DDR1/BIK pathway to induce apoptosis and suppress tumor growth." (PMID 33917302, 2021). "Previously Merestinib (LY2801653; inhibiting DDR1/2 and MET, MST1R, FLT3, AXL, MERTK, TEK, ROS1, and MKNK1/2) has shown potent anti-tumor activity in clinical trials against multiple advanced cancers." (PMID 34805157, 2021). "Overexpression of DDR1 promotes tumor cell proliferation (including regulating tumor-infiltrating CD4 + and CD8 + T cells), while silencing or knocking out DDR1 can reduce tumor cell growth." (PMID 34805157, 2021). "DDR1 regulates ERK, NOTCH, and EMT pathways, which are all involved in tumor invasion and metastatic dissemination." (PMID 34837026, 2021). "DDR1 was critical for IGF-IR endocytosis and trafficking into early endosomes, and DDR1 overexpression induced upregulation of both the IGF1 receptor (IGF1R) and the insulin receptor (IR) in normal and tumor cells." (PMID 34206590, 2021). "For example, DDR1 inhibitors targeting DDR have low IC50 values and have been shown to potently attenuate tumor growth in vitro." (PMID 34771678, 2021). "SVF secretes the cytokine Interleukin-6 (IL-6) in a DDR1-dependent manner, and SVF produced IL-6 increases tumor cell invasion in vitro." (PMID 34805157, 2021). "Although DDR1 induces an invasive cancer cell phenotype that contributes to invasion, metastasis, and therapy resistance, whether DDR1 can mediate a communication between cancer cells and stromal cells and alter the tumor microenvironment (TME) is poorly understood." (PMID 34237033, 2021). "In thyroid cancer, crosstalk between DDR1 and IGF-2/IR-A is responsible for tumor cell proliferation and invasion in 2D and 3D assays, and it is involved in the maintenance of tumor cell stemness." (PMID 33917302, 2021). "In this tumor context, we provide evidence that LRP-1 promotes cell proliferation through regulating the levels of membrane DDR1 in 3D collagen matrices." (PMID 32582700, 2020). "More recently, several ATP-site inhibitors have been developed to specifically inhibit DDR1 and/or DDR2 activity, and they display significant anti-tumor activities in several cancer models, including CRC cells." (PMID 32117772, 2020). "DDR1 and DDR2 play an important role in the tumor microenvironment which is involved in the dissemination of tumor cells." (PMID 32984031, 2020).